CLDN6 (claudin 6)
Diseases named in the same sentence as CLDN6 in open-access papers (continued):
Sharing a sentence is not in itself a finding about the gene and the disease.
hepatocellular carcinoma (13 papers, 2013 to 2025). A malignant tumor that arises from hepatocytes. "In hepatocellular carcinoma, CLDN6 is highly expressed and associated with poor prognosis (unpublished research by our group)." (PMID 32093760, 2020). "The re-expression of Claudin-6 (CLDN6) in hepatocellular carcinoma (HCC) has drawn attention as a potential target." (PMID 41425250, 2025). "However, CLDN6 was highly expressed in human hepatocellular carcinoma (hHCC) (TCGA database), and the role of CLDN6 in hHCC is still unclear." (PMID 34405008, 2021). "Therefore, this study will explore the clinical significance in liver cancer tissues of CLDN6 and its effects on the proliferation, migration and invasion abilities of human hepatocellular carcinoma (hHCC) cell lines HepG2 and Hep3B." (PMID 34405008, 2021). "Therefore, we overexpressed wt or mutated forms of CLDN6 and OCLN in hepatoma Huh-7 cells that endogenously express CLDN1, -6 and OCLN proteins." (PMID 26561856, 2015). "However, CLDN6 promotes the proliferation of human hepatocellular carcinoma cells." (PMID 34948213, 2021). "CLDN6 is highly expressed in hepatocellular carcinoma, and can promote EMT in hepatoma cells." (PMID 36620607, 2022). "In addition, CLDN6 overexpression may act as an oncogene and enhance HepG2 cell migration, invasion, and proliferation via EGFR/AKT/mTOR signaling in hepatocellular carcinoma." (PMID 36620607, 2022). "In this regard, others have shown that human PBMC transcribe CLDN-6 but not CLDN-1 and that human hepatoma Bel7402 cell line was recognized by HCVpp despite that the cells did not express CLDN-1." (PMID 23626783, 2013). "SR-B1 protein was found in T and hepatoma cell lines but not in PBMC or primary T lymphocytes, CLDN-1 in HCV-resistant PM1 T cell line and hepatoma cells only, while CLDN-6 equally in the cells investigated." (PMID 23626783, 2013).
germ cell tumor (12 papers, 2021 to 2026). A benign or malignant, gonadal or extragonadal neoplasm that originates from germ cells. "Although CLDN18.2 and CLDN6 are recognized as promising tumor-associated antigen (TAA) genes, CLDN6 is highly expressed in ovary and testicular germ cell tumors, and CLDN18.2 is highly expressed in pancreatic and stomach tumors." (PMID 40057807, 2025). "In tumor tissues, we found strong and homogeneous CLDN6 expression in desmoplastic small round cell tumors and germ cell tumors." (PMID 40149257, 2025). "Membranous CLDN6 expression was frequently detected in a subset of the pediatric tumor entities, including germ cell tumors (93% of samples with CLDN6-positive cells), nephroblastoma (64%), extracranial malignant rhabdoid tumors (50%), and AT/RTs (39%)." (PMID 41073135, 2025). "We found strong and homogeneous CLDN6 expression in desmoplastic small round cell tumors and germ cell tumors." (PMID 40149257, 2025). "In germ cell tumors, CLDN6 demonstrates highly specific expression and is strongly implicated in promoting tumor cell proliferation." (PMID 39915118, 2025). "For example, a pan-cancer analysis of CLDN6 showed it is minimally expressed in most normal adult tissues but activated in several cancers (germ cell tumors, gynecologic cancers), correlating with worse outcomes." (PMID 40687428, 2025). "High-level CLDN6 expression is commonly detectable in germ cell tumors (GCT), epithelial ovarian cancer (EOC), endometrial carcinoma and additional solid tumor indications, including rare malignancies." (PMID 37872225, 2023). "Using monoclonal antibodies against CLDN6 can repress tumor growth and extend the lifespan of testicular germ cell tumors (TGCTs) patients." (PMID 34948213, 2021). "Thus, claudin-6 is highly expressed in a number of germ cell tumors and appears to play an important role in regulating cancer progression." (PMID 35740406, 2022). "All samples with a high number of CLDN6-positive tumor cells (five extracranial germ cell tumors, two nephroblastoma and the one DSRCT) expressed also CLDN6 mRNA at >104." (PMID 40149257, 2025). "The results showed that CLDN6 was more highly expressed in germ cell tumors (28/28, 100%) and less expressed in non-germ cell tumors (64/832, 8%)." (PMID 34948213, 2021).
lymph node metastasis (12 papers, 2012 to 2026). "In their study, low CLDN6 expression was associated with more advanced tumor stages, a higher likelihood of lymph node metastasis, decreased survival rates, and overall poorer prognosis." (PMID 40687428, 2025). "Similarly, high expression of CLDN6 is associated with lymph node metastasis and lymphatic vessel infiltration in cervical adenocarcinoma." (PMID 40687428, 2025). "Moreover, we found that high CLDN6 expression was associated with age (>62 years), tumor diameter, vessel carcinoma embolus, T stage, N stage and lymph node metastasis in GC patients." (PMID 31827075, 2019). "Only one sample obtained from a cervically localized lymph node metastasis expressed high levels of CLDN6 RNA." (PMID 40149257, 2025). "We observed that patients with low CLDN6 expression exhibited a higher likelihood of lymph node metastasis." (PMID 39169280, 2024). "Among the clinicopathological factors, the high CLDN6 expression was significantly associated with surgical stage III/IV, histological type, histological grade 3, lymphovascular space involvement, lymph node metastasis and distant metastasis." (PMID 32987797, 2020). "Claudin-6 expression was inversely correlated with lymph node metastasis (P = 0.021)." (PMID 22455563, 2012). "Of the CRCs that expressed CLDN6, 75% (n = 28) had lymph node metastases, while only 46.8% (n = 79) of those negative for CLDN6 had nodal disease." (PMID 38540693, 2024). "CLDN6 expression level is lower in the cancer samples with lymph node metastasis than in those without lymph node metastasis." (PMID 27461117, 2016).
lung carcinoma (8 papers, 2015 to 2025). "The discrepancy between studies highlights the complex and possibly context-dependent role of CLDN6 in lung cancer." (PMID 40687428, 2025). "Beyond CLDN6, other claudins such as CLDN9 and CLDN12 have also been implicated in lung cancer metastasis." (PMID 40687428, 2025). "CLDN6 has been shown to regulate several signaling pathways that promote lung cancer malignant phenotypes, such as proliferation, migration, invasion, and drug resistance." (PMID 36983664, 2023). "In relation to lung cancer, current evidence suggests a role for Cldn6; however, reports disagree as to whether the presence of Cldn6 confers improved or diminished prognoses." (PMID 27763528, 2016). "CLDN6-TCAR T cells exerted potent and antigen-dependent IFNγ secretion and cytotoxicity against human CLDN6+ Colo-699-N lung cancer cells (left and middle)." (PMID 36923303, 2022).
cervical carcinoma (7 papers, 2016 to 2025). A carcinoma arising from either the exocervical squamous epithelium or the endocervical glandular epithelium. "Claudin-6 was shown to be a tumor suppressor through genetic manipulation studies in cervical carcinoma cells wherein loss of claudin-6 exacerbated cell proliferation and tumor growth." (PMID 31861759, 2019). "In contrast to claudin-1, claudin-6 is downregulated in cervical carcinoma, and expression of claudin-6 leads to decreased cell proliferation, colony formation in vitro, and tumor growth in vivo." (PMID 32197343, 2020). "In cervical cancer cells, the expression of CLDN6 was down-regulated and overexpression of CLDN6 suppressed cell proliferation, colony formation in vitro and tumor growth in vivo, which were accompanied and potentially caused by the promotion of tumor cell apoptosis." (PMID 36362009, 2022). "Similarly, CLDN6 overexpression in cervical carcinoma cells inhibits tumor growth in vitro and in vivo." (PMID 34948213, 2021). "In summary, cervical cancer progression is marked by a dynamic modulation of claudins – with early lesions showing claudin overexpression and late-stage cancers showing claudin loss (for CLDN1,2,4,7), alongside sustained or newfound expression of other claudins (CLDN6,8,9) that promote metastasis." (PMID 40687428, 2025). "Furthermore, CLDN6 knockdown relieved cell apoptosis and promoted proliferation of bovine CCs, which was consistent with previous studies in human breast epithelium cell lines and cervical carcinoma." (PMID 36362009, 2022). "In addition, the expression of CLDN6 was demonstrated to be silenced in cervical carcinoma tissues, and the restoration of CLDN6 expression suppressed cell proliferation and colony formation in cervical carcinoma cells in vitro, and tumor growth in vivo." (PMID 30219077, 2018). "These oncofetal proteins (CLDN6, normally not expressed in adult cervix) may contribute to the aggressive behavior of certain cervical cancers." (PMID 40687428, 2025).
gastric adenocarcinoma (7 papers, 2013 to 2023). "The human-derived gastric adenocarcinoma cell line AGS cells transfected with claudin-6 have increased proliferation, cell migration, and invasiveness." (PMID 36430456, 2022). "The overexpression of claudin-6, claudin-7, or claudin-9 enhanced the invasive potential of a gastric adenocarcinoma cell line." (PMID 24073219, 2013). "The aim of this study was to analyze TCGA-Stomach Adenocarcinoma (STAD) data for tumors with enhanced Cldn6 (Cldn6high) expression using several bioinformatic tools to define whether its expression is associated with a more aggressive phenotype." (PMID 36430456, 2022). "CLDN6 overexpression in the gastric adenocarcinoma cell line AGS has proved to play a significant role in cell proliferation, migration, and invasion, but very little is known about the transcription factors that regulate CLDN6 expression." (PMID 37762277, 2023). "A similar phenomenon was observed in gastric adenocarcinoma cells, where forced over expression of claudin-6, –7, and -9 increased the motility of these cells compared to non-transfected gastric adenocarcinoma cells." (PMID 23521713, 2013).
colorectal cancer (5 papers, 2022 to 2025). A primary or metastatic malignant neoplasm that affects the colon or rectum. "Claudin-2 (Cldn2) has been implicated in promoting liver metastasis in breast and colorectal cancers, while claudin-6 (Cldn6) is associated with chemotherapy resistance and poor prognosis in gastric and cervical adenocarcinomas." (PMID 40361399, 2025). "We have previously demonstrated that CLDN6 inhibits AKT phosphorylation by upregulating PTEN in colorectal cancer." (PMID 39984471, 2025). "This suggests CLDN6 may have a tumor-suppressor function in colorectal cancer, consistent with it being a developmental protein normally silenced in adult tissue." (PMID 40687428, 2025).
rhabdoid tumor (5 papers, 2012 to 2025). An aggressive malignant embryonal neoplasm usually occurring during childhood. "Although the number of MRT samples analyzed in our work is too low to allow for final conclusions about CLDN6 staining in this entity, discrepancy on the frequency of positive samples within intracranial rhabdoid tumors (AT/RTs) has been reported as varying from 100% to 29% and 39%." (PMID 40149257, 2025). "Indeed, expression of CLDN6 has previously been shown in malignant rhabdoid tumors (MRTs), Wilms tumors (WTs), hepatoblastoma, germinoma and extracranial GCT, Thus, CLDN6 could represent an important target for CAR-T cells and monoclonal antibody-based therapies in the pediatric population." (PMID 40149257, 2025).
breast tumor (4 papers, 2015 to 2024). "Data in GSE103512 showed that the level of CLDN6 and WIP in breast tumor tissues was lower than normal tissues." (PMID 36935496, 2023). "We found that all ten EMT-related genes were frequently methylated in primary breast tumours, i.e. CLDN18 (100 %), KRT85 (100 %), MIR127 (100 %), MIR433 (100 %), MIR23b (60 %), KRT83 (100 %), MST1R (60 %), BVES (60 %), CLDN6 (50 %) and HOXD10 (55 %)." (PMID 26052355, 2015). "Notably, 322 CSR transcripts were significantly elevated in breast tumours compared to healthy breast tissue, with CEACAM6 (log2FC = 8.8), KCNJ (8.4), and CLDN6 (7.6) among the most upregulated." (PMID 38306344, 2024).
gastric tumors (4 papers, 2022 to 2025). "CLDN6 is a cellular adhesion protein that is abundantly expressed in gastric tumors tissues and cell lines, and is associated with a poor prognosis." (PMID 35281827, 2022). "We believe that our study provides an entry point for the identification of new markers and regulatory pathways in claudin-6 expressing gastric tumors." (PMID 36430456, 2022). "Compared with benign tissues, the CTLA4 and ENTPD2 were highly expressed in gastric tumor tissues, while the AKR1B1, CLDN6, EMB, GPR15 and VWF were highly expressed." (PMID 37066015, 2023).
melanoma (4 papers, 2023 to 2025). A malignant, usually aggressive tumor composed of atypical, neoplastic melanocytes. "BNT116 encodes six NSCLC-associated antigens: melanoma antigen gene A3, A4, and C1 (MAGE A3, A4, and C1); claudin 6 (CLDN6); Kita-Kyushu lung cancer antigen-1 (KK-LC-1); and preferentially expressed antigen of melanoma (PRAME)." (PMID 41007751, 2025).
ovarian tumors (4 papers, 2021 to 2025). "SC-004 is another pyrrolobenzodiazepine-based antibody drug conjugate that consists of a monoclonal antibody targeted to claudins 6 and 9 (CLDN6/9), tight junctional proteins, that are overexpressed in ovarian tumors, bound to a pyrrolobenzodiazepine dimer." (PMID 34683998, 2021). "Building from preclinical studies, researchers opened a clinical trial evaluating CLDN6 CAR-T +/- CARVac in patients with refractory metastatic CLDN6-positive solid tumors (germ cell and ovarian tumors predominantly), which has reported interim results for 22 of the patients enrolled." (PMID 38371623, 2024). "The correlation analysis results also indicate that EpCAM and CLDN6 are only co-expressed in ovary tumor, but not in other tumors, such as stomach and Colorectal tumors." (PMID 40057807, 2025). "Another group generated a humanized mAb targeting ECL2 (CLDN6-23) and showed significant inhibition of tumor growth in xenograft models of bladder cancer (UMUC4) and small cell lung cancer, with more modest responses observed in ovarian tumors." (PMID 38371623, 2024).
acute myeloid leukemia (3 papers, 2021 to 2025). Acute myeloid leukemia (AML) is a group of neoplasms arising from precursor cells committed to the myeloid cell-line differentiation. "Based on transcriptomic data analyzed in this work, CLDN6 expression is expected in several samples of rare subtypes of acute myeloid leukemia (AML), namely acute megakaryoblastic leukemia and core-binding factor AML." (PMID 40149257, 2025).
colon cancer (3 papers, 2021 to 2024). "This is different from the low expression of CLDN6 in other digestive system tumors, such as gastric 29 and colon cancer." (PMID 34405008, 2021). "In colon cancer, CLDN6 activates the TYK2/STAT3 pathway, which might suppress the migration and invasion abilities of colon cancer cells." (PMID 38731853, 2024).
esophageal cancer (3 papers, 2021 to 2025). A primary or metastatic malignant neoplasm involving the esophagus. "We furthermore observed exclusive upregulation of several collagens (COL1A1, -9A1, -12A1, -27A1) in esophageal cancers with high CLDN6 levels." (PMID 37592303, 2023).
esophageal squamous cell carcinoma (3 papers, 2017 to 2025). Esophageal squamous cell carcinoma (ESCC) is a type of esophageal carcinoma (EC) that can affect any part of the esophagus, but is usually located in the upper or middle third. "Similar to our current results, CLDN6 has been found to be silenced by methylation in esophageal squamous cell carcinoma." (PMID 28867761, 2017).
invasive ductal carcinomas (3 papers, 2012 to 2017). "Our pervious studies have confirmed that CLDN6 is significantly downregulated in breast invasive ductal carcinoma which correlates with lymphatic metastasis." (PMID 29116019, 2017). "Immunohistochemical analysis showed that ASK1 expression was significantly related with that of claudin-6 in breast invasive ductal carcinomas (P < 0.05)." (PMID 22925655, 2012). "Immunohistochemical analysis was performed to evaluate the ASK1 protein expression and the correlation between ASK1, claudin-6 and clinicopathological features in 85 samples of breast invasive ductal carcinomas (IDC)." (PMID 22925655, 2012). "Statistical analysis revealed that claudin-6 expression was positive correlated with ASK1 expression in breast invasive ductal carcinomas (P = 0.0016)." (PMID 22925655, 2012). "However, the expression of claudin-6 in breast invasive ductal carcinomas and correlation with clinical behavior or expression of other markers is unclear." (PMID 22455563, 2012). "We have found that the expression of claudin-6 was reduced in breast invasive ductal carcinomas." (PMID 22925655, 2012). "Claudin-6 protein expression was reduced in breast invasive ductal carcinomas (P < 0.001)." (PMID 22455563, 2012).
lung adenocarcinoma (3 papers, 2019 to 2023). A carcinoma that arises from the lung and is characterized by the presence of malignant glandular epithelial cells. "The nuclear localization of claudin-2 and claudin-6 has been linked to enhanced cell proliferation via promotion of cell cycle progression in lung adenocarcinoma cells." (PMID 31717460, 2019). "In conclusion, we identified GULPsig, consisting of IGF2BP1, IGF2BP3, SMC1B, CLDN6, and LY6K, as a potential prognostic signature for lung adenocarcinoma patients." (PMID 37655157, 2023).
non-small cell lung carcinoma (3 papers, 2017 to 2025). A group of at least three distinct histological types of lung cancer, including non-small cell squamous cell carcinoma, adenocarcinoma, and large cell carcinoma. "Claudins 1, 3, 4, 5, 7, 8, and 18 are expressed in human bronchi and bronchioles whereas claudin-6 expression may be an effect of immortalization of the CFBE41o- epithelial cell line as it has been reported in non-small cell lung cancer and in developing lung tissue." (PMID 32161586, 2020).
hepatitis C (2 papers, 2019 to 2021). "CLDN6 has important biological functions, and its abnormal expression is associated with Hepatitis C infection." (PMID 31827075, 2019).
liver cancer (2 papers, 2021 to 2022). An epithelial or non-epithelial malignant neoplasm that arises from the liver. "In previous experiments, we found that CLDN6 was highly expressed in human liver cancer tissues, but the expression of CLDN6 in human liver cancer cells and its specific role in the biological behavior of liver cancer cells are still unclear." (PMID 34405008, 2021). "This study mainly investigated the clinical significance of CLDN6 expression in human liver cancer tissues and the effect of CLDN6 on the tumor biological behavior of hHCC cells HepG2 and Hep3B through EMT." (PMID 34405008, 2021). "Therefore, we speculated that the upregulated expression of CLDN6 in liver cancer tissues may promote the occurrence and development of hHCC." (PMID 34405008, 2021).